BDNF (brain derived neurotrophic factor)
Diseases named in the same sentence as BDNF in open-access papers (continued):
Sharing a sentence is not in itself a finding about the gene and the disease.
Stroke (continued). "The present study was designed to investigate the regional effect of treadmill exercise on brain BDNF in intact and stroke brains." (PMID 22962604, 2012). "We found evidence that BDNF concentrations are increased after neonatal HI (unpublished data) as well as in the post-stroke milieu." (PMID 23251608, 2012). "In a recent paper elevated levels of BDNF have been observed at 4 h and 24 h after stroke but the putative role of BDNF as a peripheral marker in patients has been questioned as significant changes have not been observed in the first 4 days." (PMID 23284893, 2012). "Using a model of cortical ischemic stroke, the present study is the first to compare the effects of treadmill exercise on the levels of mature BDNF (mBDNF) and its precursor proBDNF in control versus stroke brain." (PMID 22962604, 2012). "BDNF genotype and promoter methylation percentages by stroke outcome status at 2 week and at 1 year." (PMID 23240009, 2012). "In conclusion, the present results are consistent with the involvement of BDNF-dependent plasticity in the beneficial effect of treadmill exercise after stroke." (PMID 22962604, 2012). "Future studies will aim to investigate the interaction of stroke combined to exercise on BDNF processing and to understand the mechanisms involved in BDNF overexpression by cerebral endothelium after exercise." (PMID 22962604, 2012). "Our data show that stroke alone changed BDNF metabolism selectively in Cx1 (the cortical region centered on the lesion)." (PMID 22962604, 2012). "Partial correlations between BDNF promoter methylation percentages and scores on stroke assessment scales." (PMID 23240009, 2012). "It has been shown that the rate of neuronal production is enhanced after stroke and traumatic brain injury, and BDNF, the mediator of neurogenesis in rodent models of stroke, is upregulated by CR." (PMID 21910904, 2011). "Whereas brain-derived neurotrophic factor (BDNF) levels are measured in the brain in animal models of stroke, neurotrophin levels in stroke patients are measured in plasma or serum samples." (PMID 22195050, 2011). "Stroke significantly increased brain BDNF levels at 4 h and 24 h post-embolization, but the levels did not correlate with the degree of embolization in any of the three time groups of stroke rats." (PMID 22195050, 2011). "The studies consistently showed that brain BDNF levels increased after stroke, suggesting that BDNF promoted post-lesional plasticity." (PMID 22195050, 2011). "As BDNF levels are 200 times higher in serum than in plasma (in rats and humans), we suggest that severe stroke-induced elevation in plasma BDNF levels is too low to induce detectable changes in serum." (PMID 22195050, 2011). "The interpretation of circulating BDNF level in stroke patients has been made on the basis of the assumptions that circulating BDNF levels mirror brain BDNF levels." (PMID 22195050, 2011). "Our present animal study in which BDNF levels were measured before and after embolization in the same rats offers the unique opportunity to directly investigate the effect of stroke on circulating BDNF levels." (PMID 22195050, 2011). "The corollary is that that only post-mortem analysis of the ischemic brain will document the effect of human stroke on brain BDNF levels." (PMID 22195050, 2011). "The effect of stroke on circulating BDNF levels was assessed from the serial measurement of serum and plasma levels in the groups “stroke 8 ds” and “stroke 8 d”, respectively." (PMID 22195050, 2011). "In contrast, a positive correlation was observed between plasma BDNF levels and stroke severity in the acute stage of stroke (4 h post-embolization)." (PMID 22195050, 2011). "The present study was designed to investigate the meaning of circulating BDNF levels in stroke patients." (PMID 22195050, 2011).
Stroke (continued). "This study, which is the first to document circulating BDNF levels in an animal model of stroke, was designed to answer the following questions: 1) does stroke induce changes in circulating BDNF levels?" (PMID 22195050, 2011). "The primary mediators of ischemic tissue recovery after stroke are BDNF and vascular endothelial growth factor (VEGF)." (PMID 21910904, 2011). "In order to help the interpretation of circulating BDNF levels in stroke patients, we measured BDNF levels in plasma, serum, and brain before and up to 8 days after the induction of embolic stroke in rats." (PMID 22195050, 2011). "Further clinical studies are needed to evaluate the reliability of plasma BDNF as an early biological marker of stroke severity." (PMID 22195050, 2011). "In the interpretation of circulating BDNF levels it was assumed that BDNF levels increased in the brain of stroke patients as observed in animals and that circulating BDNF levels mirrored brain BDNF levels." (PMID 22195050, 2011). "On mRNA level, BDNF inhibited mRNA expression of brain TNF-α after stroke at both 6 h (0.39 ± 0.01 versus 1.00 ± 0.06, n = 6, P < .05) and 24 h (0.77 ± 0.04 versus 0.91 ± 0.06, n = 6, P < .05) of reperfusion." (PMID 21490702, 2010). "Furthermore, Tregs promote oligodendrocyte differentiation and myelination to restore white matter integrity, and facilitate the delivery of brain‐derived neurotrophic factor (BDNF) to the site of brain injury to support neurological recovery after stroke." (PMID 41552852, 2026). "Circulating levels of BDNF are substantially altered following stroke." (PMID 41598337, 2026). "While multiple studies confirm that low acute-phase BDNF serves as a robust independent predictor of global disability, showing a linear relationship with mRS scores up to 7 years following stroke, modern neurorehabilitation demands more granular assessment metrics." (PMID 41598337, 2026). "Interestingly, the decline in BDNF levels post-stroke was significant in the control group but attenuated by the intervention, indicating a beneficial effect of exercise." (PMID 40520612, 2025). "Our findings contradict a meta-analysis indicating that MBIs may elevate peripheral BDNF in non-stroke populations." (PMID 40283415, 2025). "Discrepancies may stem from exercise intensity, as high-intensity aerobic exercise is most effective for increasing BDNF in patients with stroke." (PMID 40283415, 2025). "Multi-modal exercise has been demonstrated to substantially enhance cognitive function in individuals who have suffered from strokes, enhancing attention, language fluency, and logical memory, while simultaneously stimulating the brain, increasing BDNF levels, and improving cerebral blood flow." (PMID 40959502, 2025). "Additionally, metformin stimulates neurogenesis by increasing the expression of the brain-derived neurotrophic factor (BDNF), which is essential for post-stroke neural plasticity and functional recovery." (PMID 40710317, 2025). "Thus, the activation of astrocytes induced by OptoSTIM1 implies multiple BDNF actions involved in post-stroke recovery." (PMID 39889003, 2025). "Thus, neuroplasticity is a key aspect of recovery, and brain-derived neurotrophic factor (BDNF) is one mediator of post-stroke aphasia recovery that has gained attention in recent years." (PMID 40658687, 2025). "Some authors have reported that the BDNF genotype may impact the outcome of a rehabilitation intervention and the cognitive and functional status of the stroke population." (PMID 40141452, 2025). "Previous research has demonstrated that intranasal BDNF may positively impact the inflammatory response following a stroke." (PMID 40895108, 2025). "Long-term running increases BDNF expression, a key mediator of synaptic plasticity and neuronal survival, which may facilitate cognitive recovery after stroke." (PMID 40969674, 2025).
Stroke (continued). "Additionally, treadmill exercise in rodent models of stroke results in a fourfold increase in hippocampal BDNF expression (p < 0.05), which enhances synaptic plasticity and neurogenesis." (PMID 40256392, 2025). "At the molecular level, we found a significant increase in the expression of BDNF in both neurons and astrocytes in the bilateral motor cortex following OptoSTIM1 stimulation, consistent with previous studies that reported elevated BDNF expression in the motor cortex during post-stroke recovery." (PMID 39889003, 2025). "Pair-housing could reverse the detrimental effects of post-stroke social isolation mediated by brain-derived neurotrophic factor via downstream MAPK/ERK signalling." (PMID 39753750, 2025). "A sub-group analysis revealed a significant reduction in the control group (Ln, p < 0.02, 39% reduction), but not in the intervention group (Ln, p < 0.40, 12% reduction), signifying a positive role of physical exercise in resisting post-stroke decline in BDNF levels." (PMID 40520612, 2025). "One possible contributor to the limited effects of CE on BDNF could be the stress and inflammatory processes characterizing early post-stroke stages." (PMID 40462267, 2025). "As a crucial component of non-pharmacological treatment, physical activity interventions significantly enhance cognitive rehabilitation outcomes in stroke patients by increasing serum brain-derived neurotrophic factor (BDNF) levels and improving neurological deficits." (PMID 40959502, 2025). "Discrepancies remain about changes in BDNF levels at post-stroke follow-up in plasma/serum." (PMID 40520612, 2025). "B cells are a main source of BDNF, which is essential for neuronal function and may promote early neuroprotection after a stroke." (PMID 41427019, 2025). "BDNF is essential for post-stroke neural repair in the brain, including in the DG and amygdala." (PMID 40490588, 2025). "In terms of the molecular mechanisms, exercise induces BDNF and Scg2 expression in the brain and spinal cord and could support the induction of rewiring and recovery after stroke." (PMID 40191711, 2025). "Notably, a recent meta-analysis identified exercise intensity as a critical variable, highlighting high-intensity aerobic exercise as particularly effective in elevating BDNF levels among patients with stroke." (PMID 40283415, 2025). "Recent research demonstrated that BDNF is involved in the neuroprotection, neurogenesis and neuroplasticity, and it has been identified as a key factor in motor learning and recovery after stroke." (PMID 40720525, 2025). "Given its central role in regulating neuroplastic processes and brain repair in animal models, brain-derived neurotrophic factor (BDNF) has been targeted as a potential biomarker for stroke recovery in humans, with interventions upregulating BDNF holding therapeutical potential." (PMID 40462267, 2025). "Nonetheless, our data shows that BDNF levels are reduced post-stroke and physical activity could be a good tool to resist the reduction of plasma BDNF levels which may counter post-stroke depression along with cardioprotective effects." (PMID 40520612, 2025). "While pre-PCI brain-derived neurotrophic factor (BDNF) levels predicted this reduction, it was the post-PCI renalase level itself (≥35 ng/mL) that was associated with a higher long-term risk of myocardial infarction, stroke, and death." (PMID 41157254, 2025). "tDCS can inhibit the overexpression of BDNF/TrkB in the descending pain pathway after stroke." (PMID 40809334, 2025). "This indicates that genetic variations in BDNF may significantly impact recovery trajectories and underscore the importance of personalizes approaches in stroke rehabilitation." (PMID 40492169, 2025). "A patient’s brain-derived neurotrophic factor genotype may influence their post-stroke aphasia recovery." (PMID 40658687, 2025).
Stroke (continued). "Furthermore, IH has been documented to upregulate hippocampal brain-derived neurotrophic factor (BDNF) expression, and rescue impairments of neurogenesis and memory in models of stroke and Alzheimer’s pathology." (PMID 38985935, 2024). "Since BDNF plays a vital role in multiple aspects of neurodevelopment, including learning and memory, the BDNF genotype may predict cognitive function following stroke." (PMID 38707431, 2024). "Future research in this area could focus on elucidating the mechanistic pathways linking BDNF to lipid metabolism and exploring the potential of BDNF as a therapeutic target in stroke prevention and treatment." (PMID 38397057, 2024). "The authors observed the upregulation of BDNF and its TrkB receptor at the hippocampal level of the ischemic hemisphere, thus speculating that modulation of BDNF signaling pathway might be critical in functional recovery after stroke." (PMID 40153582, 2024). "Additionally, while tDCS has been shown to increase serum BDNF levels in stroke patients, its efficacy in treating patients with PSSD remains underexplored." (PMID 39539650, 2024). "In stroke, BDNF has been largely shown to play a protective role." (PMID 38469139, 2024). "BDNF exhibits anti-inflammatory properties that protect against stroke." (PMID 38707431, 2024). "Other genes associated with stroke and/or VaD risk include angiotensin-converting enzyme (ACE; only stroke), alpha-1 antichymotrypsin (ACT), glutamate-cysteine ligase modifier (GCLM), endothelial nitric oxide synthase (NOS3), and brain-derived neurotrophic factor (BDNF)." (PMID 39063013, 2024). "Furthermore, the less severe IH protocols were also documented to enhance hippocampal BDNF expression, and rescue impairments of neurogenesis and memory in models of strokes and Alzheimer’s pathology." (PMID 38985935, 2024). "Additionally, The BDNF: CCL11(AUC = 1.00) reflects the balance between neuroprotection and neuroinflammation, relevant for managing pain, cognitive issues and stroke risk in SCD, consistent with previous findings." (PMID 39749215, 2024). "BDNF supports the growth and differentiation of the neurons by activating the TrkB receptor, fostering new neuronal connections crucial for recovery after a stroke." (PMID 39057499, 2024). "Additionally, combining BDNF with other stroke treatment strategies has been reported to be beneficial." (PMID 39095888, 2024). "However, the direct link between lipid levels and BDNF levels in stroke patients remains underexplored." (PMID 38397057, 2024). "In stroke models, BDNF in the brain generally increases after injury." (PMID 38397427, 2024). "Moreover, Tregs secrete neurotrophic factors such as brain‐derived neurotrophic factor, which plays a crucial role in neural repair and regeneration following a stroke." (PMID 38323746, 2024). "In our present study of stroke patients, we found that the high BDNF group (≥3.227 ng/mL) had significantly higher levels of HbA1C and TG; ratios of TC/HDL-C, LDL-C/HDL-C, and TG/HDL-C; and percentages of hyperlipidemia (60%), as well as lower levels of HDL-C and platelets." (PMID 38397057, 2024). "BDNF plays a significant role in the prognosis, pathogenesis, and rehabilitation in stroke." (PMID 39469715, 2024). "Importantly, blocking BDNF for 28 days after stroke in rats negated the effects of rehabilitation on functional recovery, suggesting the key role of BDNF in stroke recovery." (PMID 38397427, 2024). "By activating the forkhead box O (FoxO) and SIRT1/FoxO1 signaling pathways, exercise could reduce cell death and neural loss, increase brain-derived neurotrophic factor (BDNF) production, and promote neuroplasticity and functional recovery after the stroke." (PMID 38992073, 2024). "BDNF was also positively correlated with the severity of stroke as assessed by the NIHSS." (PMID 39001884, 2024). "Genome-wide association studies (GWASs), however, have not confirmed BDNF’s association with stroke recovery." (PMID 38397427, 2024).
Stroke (continued). "The level of BDNF in serum from PSD patients at 3-6 months after stroke onset is lower than that from control stroke patients, suggesting that BDNF level in serum may be used as a predictor of PSD." (PMID 38421829, 2024). "In addition, we advocate further exploration of the clinical and pharmacological applications of BDNF for stroke and PSCI, which we believe is a powerful way forward." (PMID 38845616, 2024). "Therefore, modulation of BDNF expression is promising for neurogenesis and protrusion generation in damaged areas after stroke." (PMID 36741282, 2023). "It has been shown that intracranially produced BDNF can cross the blood-brain barrier; therefore, the level of peripheral BDNF after stroke may reflect central BDNF levels." (PMID 37123377, 2023). "Intravenous BDNF injection after stroke could enhance neuronal remodeling, leading to improved functional motor recovery (rotarod, beam balance, neuroscore)." (PMID 35821455, 2023). "In stroke and heart failure, altered BDNF levels or the Val66Met genotype could be recommended as biomarkers for predicting CVD risk." (PMID 38137853, 2023). "The value of BDNF as a biomarker for CVDs other than stroke is more complex." (PMID 38137853, 2023). "In addition, it has been shown that patients with significantly lower serum BDNF levels and increased brain infarct volume after stroke have a worse functional outcome of stroke." (PMID 37534033, 2023). "Serum BDNF levels are therefore a signal of maladaptation or dysfunction of the body leading to stroke and could therefore be used as a potential biomarker for PSD." (PMID 37895349, 2023). "In stroke models, activated astrocytes are found to enhance the expression of brain-derived neurotrophic factor (BDNF), promote the differentiation of neural precursor cells derived from the central nervous system, and improve the survival and engraftment rates of early NSCs." (PMID 37893146, 2023). "BDNF has been shown to improve the ability of the brain to repair after a stroke." (PMID 37927446, 2023). "Administering MSCs after stroke improves functional neurologic outcomes, reduces infarct sizes, increases survival of neurons, and normalizes biochemical parameters through modulating ER stress-mediated apoptosis through the BDNF/TrkB signaling pathway." (PMID 37008060, 2023). "Five studies investigated possible altered BDNF levels in patients with stroke." (PMID 37895349, 2023). "Brain-Derived Neurotrophic Factor (BDNF) is a member of the neurotrophin family, which is involved in neuroprotection, neurogenesis and neuroplasticity, and has been identified as a key regulator of motor learning and rehabilitation after stroke." (PMID 37333888, 2023). "The meta-analysis of studies on biomarker changes after stroke rehabilitation revealed that rehabilitation can significantly increase the concentration of serum BDNF and NE, and peripheral blood SOD, ALB and HB, and CAT, and decrease the biomarkers of serum ET, glutamate, and TNF-α." (PMID 37731856, 2023). "Furthermore, the concentration of brain-derived neurotrophic factor (BDNF) significantly increased in the treatment group, and this was significantly correlated to the functional improvement after stroke." (PMID 37731856, 2023). "In addition, multiple studies have established numerous neuroprotective effects of T3 after stroke, including a decrease in embryonic neuronal mortality and glutamate transfer to brain cells, as well as an increase in brain-derived neurotrophic factor (BDNF)." (PMID 37606393, 2023). "Currently, BDNF is shown to be an optimal biomarker for stroke." (PMID 38137853, 2023). "Additionally, we previously reported that increased BDNF expression was involved in the neuroprotective effects of preventive exercise, with an observed reduction in stroke volume as well as motor-sensory dysfunction." (PMID 36750711, 2023).